ATG5 (autophagy related 5)
Diseases named in the same sentence as ATG5 in open-access papers (continued):
Sharing a sentence is not in itself a finding about the gene and the disease.
lung carcinoma (continued). "The importance of autophagy in the initiation and/or progression of KRAS- or BRAF-driven lung cancer was revealed through analysis of GEM models in which deletion of key autophagy genes (Atg5 or Atg7) accompanied the initiation of oncoprotein expression." (PMID 39213022, 2024). "In lung cancer mice with Atg7 or Atg5 deletions, tumor size decreased compared with wild type Atg7 or Atg5 mice." (PMID 38067169, 2023). "Hypoxia-induced PVT1 expression can enhance cisplatin chemoresistance in lung cancer by autophagy through the PVT1/miR-140-3p/ATG5 pathway." (PMID 37255541, 2023). "The chemical inhibition of autophagy by 3-methyadenine (3-MA) or Bafilomycin A1 (Baf A1) and the genetic inhibition of autophagy by knocking down Atg5 or Atg7 hampered the suppressive effects of fluvastatin on bone metastasis of lung cancer cells." (PMID 37190124, 2023). "For example, in the lung cancer models of Cre–activatable KrasG12D or BrafV600E, the conditional KO of ATG5 or ATG7 accelerated tumor initiation which were, however, diverted to benign oncocytoma." (PMID 36187114, 2022). "Here, we observed that digitoxigenin and digoxin promote cell death of A549 lung cancer cells and have a pro-survival ATG5 and BECLIN-1-dependent autophagic activity in RNVCs." (PMID 35159285, 2022). "ATG5 was the key regulatory gene of the autophagy signaling pathway, and our results suggested that the hypoxia/PVT1/miR-140-3p signaling axis regulated the chemoresistance ability via regulating ATG5 expression in lung cancer." (PMID 35256612, 2022). "In this study, Chen and colleagues demonstrated that cisplatin treatment induced autophagy by upregulating ATG5 expression, which provides resistance to cisplatin-induced apoptosis of lung cancer cells." (PMID 36358691, 2022). "Together, our results present a new mechanism that PVT1 is a hypoxia-related lncRNA and participates in the hypoxia-induced chemoresistance process by regulating the autophagy signaling pathway via PVT1/miR-140-3p/ATG5 axis in lung cancer." (PMID 35256612, 2022). "ATG5 is an autophagy family protein that is found to accelerate tumorigenesis by removing damaged molecules or organelles in lung cancer." (PMID 36358691, 2022). "PVT1 participated in hypoxia-induced chemoresistance of lung cancer cells by promoting the autophagy signaling pathway via the PVT1/miR-140-3p/ATG5 axis." (PMID 35256612, 2022). "As expected, the knockdown of ATG5 significantly inhibited the conversion of LC3I to lipidated LC3II upon CVB-D treatment in all lung cancer cells." (PMID 34072333, 2021). "For example, deletion of Atg5 or Atg7 in Pten-/--driven prostate cancer, KrasG12D- or BrafV600E-driven lung cancer, or KrasG12D-driven pancreatic ductal adenocarcinoma, suppresses tumor growth." (PMID 32308763, 2020). "The protein expression of p62 (also called sequestosome-1) and Atg5 (autophagy protein 5) was found in 44 out of 118 (37.3%) and 70 out of 131 (53.4%) patients with primary lung cancer, respectively." (PMID 29545906, 2018). "The ATG5-dependency of TRAF3 levels and transcriptional events were also demonstrated by CRISPR-Cas9 deletion of ATG5 in a second RAS-mutant lung cancer line, NCI-H23." (PMID 29146913, 2017). "The tumor growth promoting benefits of Atg5 or Atg7 loss of expression has also been demonstrated in several experimental models, such as in the BRAFV600E driven lung carcinomas or in the KRASG12D or driven pancreatic cancer." (PMID 26416459, 2015). "Future work will be required to address the molecular mechanism by which NASTRp suppresses autophagy or related molecules such as ATG7, ATG5 and p62 in lung cancers." (PMID 25897662, 2015). "X Zhou in 2018 demonstrated that in GOT1-null 143B osteosarcoma cells or GOT1 siRNA knockdown in A549 lung cancer cells resulted in the elevated expression of autophagy-related genes (ATG5 and Beclin1) and increased secretion rate of lactate compared with wild type cells." (PMID 37190124, 2023).
lung carcinoma (continued). "Moreover, silencing the Atg5 or Atg7 gene of lung cancer cells harboring active-mutant Rab37 (Q89L) led to decreased autophagy activity and TIMP1 secretion." (PMID 36457117, 2022). "ATG5 knockdown considerably reduced the inhibitory effect of TBs-C on lung cancer cells." (PMID 35529455, 2022). "Our results provide a better understanding of hypoxia-induced chemoresistance and the hypoxia/PVT1/miR-140-3p/ATG5/autophagy signaling axis may be a novel treatment target for lung cancer." (PMID 35256612, 2022). "Moreover, TCGA data mining and analysis show that Atg5 and Zeb1 are poor prognostic markers of lung cancer." (PMID 33468994, 2021). "Moreover, The Cancer Genome Atlas (TCGA) data mining and analysis show that Atg5 and Zeb1 are poor prognostic markers of lung cancer." (PMID 33468994, 2021). "In lung cancer, we found that more than 40% of samples (61 out of 131) had low expression of Atg5 protein and tumors with higher expression of Atg5 usually were well differentiated; however, this correlation has not yet reached statistical significance (p = 0.069)." (PMID 29545906, 2018). "Interestingly, when lung cancer cells were treated by 3-MA or ATG5 siRNA under hypoxia, they became sensitive to cisplatin, similar to the cells under normoxia." (PMID 26201611, 2015). "For example, some studies demonstrated that targeting autophagy may be used in the future for the treatment of lung cancer because the disruption of autophagy via the inhibition of Atg5 and Beclin 1 may promote cisplatin-induced apoptotic cell death in A549 human lung cancer cells." (PMID 32802131, 2020). "Treatment of lung cancer cells with SM-3 resulted in autophagic cell death, as evidenced by the conversion of LC3I to LC3II, along with increased levels of ATG7, ATG5, and p62." (PMID 40287470, 2025). "MEN1-KD also inhibited the mRNA levels of ATG5, SQSTM1, and MAP1LC3B and decreased the protein levels of P62 and LC3B-II in another lung cancer cells (p < 0.05)." (PMID 40057469, 2025). "Overall, in lung cancer cells treated with SM-3, there was a significant conversion of LC3B-I to LC3B-II, along with increased levels of ATG7, ATG5, and p62." (PMID 40287470, 2025). "In lung cancer, for NSCLC, METTL3 promotes autophagy by upregulating the expression of LC3B, ATG5, and ATG7, protecting drug-resistant cells from death and leading to the development of resistance to gefitinib." (PMID 39468015, 2024). "Gefitinib was shown to promote autophagy in lung cancer cell lines, as indicated by LC3II lysosomal localization, increased ATG5 and ATG7 expression at the mRNA or protein levels, and reduced phosphorylation of the PI3K/Akt/mTOR pathway." (PMID 39272847, 2024). "Conversely, CHIL31 depletion decreased the conversion from LC3-I to LC3-II in lung cancer cell lines as well as the expression of GABARAPL1, ATG5, p62, and Beclin-1." (PMID 37340009, 2023). "In this study, we analyzed the clinical influence of five autophagy-related genes including LC3A, LC3B, Beclin-1, Atg5, and p62 and investigated the epigenetic regulation of one of the autophagy genes LC3A in human lung cancer." (PMID 29545906, 2018). "We have previously reported for the first time that hypoxic lung carcinoma cells can evade CTL-mediated killing by activating autophagy and that targeting autophagy by silencing ATG5, and Beclin1 was sufficient to restore their CTL-mediated killing." (PMID 29922284, 2018). "In osteosarcoma, lung carcinoma, and neuroblastoma cells, GO and GNF increased the protein levels of ATG3, ATG5, and/or ATG7, which are required for lipidation of ATG8 family proteins, including LC3, and their subsequent association with the membrane of autophagic vesicles." (PMID 34439299, 2021). "To clarify whether CAFs autophagy is responsible for lung cancer cell EMT process, we inhibited CAF autophagy by inhibitors or ATG5 knockdown, then collected CAF-CM and cultured lung cancer cells." (PMID 34552063, 2021).
lung carcinoma (continued). "However, the alteration of the other autophagy-regulating proteins (Atg5, Atg12, and Beclin-1) was not significantly detected in human lung cancer cells cultured with 50 μM cisplatin compared to those non-treated control cells." (PMID 34321115, 2021). "Icotinib increased ATG3, ATG5, and ATG7 expression, but without affecting Beclin-1, VPS34 and ATBG14 levels in icotinib-resistant lung cancer cells." (PMID 35690866, 2022). "In line, here, we showed that siRNAs against: ATG5, ATG7, or Beclin1 introduced to normoxic or hypoxic lung cancer cells prior to CIS treatment, did not changed their ability to induce senescence or senescence escaping." (PMID 35127467, 2021).
gastric cancer (50 papers, 2014 to 2025). A primary or metastatic malignant neoplasm involving the stomach. "It was also found that ATG5 point mutations are identified in gastric cancer, colorectal cancer, and HCC." (PMID 38353395, 2024). "A large amount of existing genetic researches have revealed that rare variants of ATG5 are associated with cancers including colon cancer, stomach cancer, and prostate cancer, Parkinson disease, and other complex illnesses." (PMID 35518570, 2022). "Somatic point mutations of Atg5 have been found in patients with gastric cancer, colorectal cancer and hepatocellular carcinoma." (PMID 34829743, 2021). "The homozygote deletion of ATG5 predisposed to liver tumors with high penetrance mouse model; the somatic point mutations of ATG5 are also identified in 135 patient samples of gastric cancer, colorectal cancer, and hepatocellular carcinoma." (PMID 31969156, 2020). "Concomitantly, the somatic mutation of atg5 is presented in gastric cancers although the incidence is quite low (1.5%; 2/135)." (PMID 26910278, 2016). "Overexpression of ATG5 is associated with aggressive tumors in squamous cell carcinoma, colorectal and prostate cancers and chemoresistant tumors in gastric cancer." (PMID 27120789, 2016). "Mechanically, it has been demonstrated that the level of MALAT1 was lower and miR‐30e was upregulated, which caused suppression of autophagy‐related genes 5 (ATG5), and subsequently inactivated autophagy‐related chemoresistance in gastric cancer cells following propofol treatment." (PMID 32596964, 2020). "In the study, we demonstrated that PCA induced tumor suppressive autophagy, and blocking autophagy by si-ATG5 promotes survival in gastric cancer." (PMID 40260299, 2025). "It is reported that FEZF1-AS1 promotes the development of chemoresistance in gastric cancer cells by upregulating ATG5." (PMID 40778223, 2025). "In the present study, gastric cancer cells showed increased expression of genes involved in the autophagy process, such as ATG5 and SQSTM1, after exposure to NSC305787." (PMID 38972247, 2024). "DIM inhibited the proliferation of gastric cancer cells through the miR-30e/ATG5 pathway involved in autophagy control." (PMID 36438802, 2022). "Consistently, the latest research also demonstrated that the expression of ATG5 was also regulated by miR-140-3p in gastric cancer progression." (PMID 35256612, 2022). "In another study, curcumin inhibited LC3I expression, and enhanced LC3II, Beclin1, Atg3 and autophagy related 5 (Atg5) expression in gastric cancer SGC-7901 and BGC-823 cells." (PMID 36009200, 2022). "lncRNA MALAT1 has also been found to be highly expressed in cisplatin-resistant AGS and HGC-27 gastric cancer cells and promotes autophagy through suppression of the miR-30b/ATG5 and miR-30e/ATG5 axes, thereby reducing cisplatin sensitivity." (PMID 35327655, 2022). "The high expression of ATG5 is closely related to the poor prognosis and drug resistance of gastric cancer." (PMID 32477008, 2020). "In gastric cancer patients who received epirubicin, cisplatin, and 5-FU adjuvant chemotherapy, up-regulated expression of ATG5 was identified as an important molecular feature of chemoresistance." (PMID 29382381, 2018). "We monitored the accumulation of LC3B, Beclin-1, and ATG5 and the downregulation of p62 levels in gastric cancer cells." (PMID 29844404, 2018). "In this study, DSGOST and TJ-38 induced autophagy by enhancing LC3-II and ATG5 and reducing p62 in gastric cancer cells, thus contributing to chemoresistance." (PMID 29844404, 2018). "Meanwhile, increased expression of ATG5 was also significantly correlated with adverse prognosis and chemo-resistance in gastric cancer." (PMID 29207660, 2017). "It should be noted that the protein expression of Atg5 is lost in 21.0% (21/100) of the gastric cancers." (PMID 26910278, 2016).
gastric cancer (continued). "Consistent with this notion, sustained expression of Atg5 is detected in chemoresistant gastric cancer cell line, and downregulation of Atg5 sensitizes chemoresistant cells to drug therapy." (PMID 26910278, 2016). "Furthermore, PCA induced tumor suppressive autophagy in both gastric cancer cells, and blockage of the autophagy by silencing ATG5 can partially reverse the proliferation inhibition of PCA." (PMID 40260299, 2025). "Consistent with the functions of ATG5 in lysosomal exocytosis, we found that its knockdown led to enhancement of lysosomal exocytosis in gastric cancer cells, implicating the regulatory interplay between autophagy and lysosomal exocytosis, while the underlying mechanisms deserve further studies." (PMID 40995693, 2025). "Similarly, colorectal cancer SW480 and gastric cancer AGS cell lines also showed decreased cell survival rates by shRNA silencing Atg5 expression or CRISPR knockout Atg5 gene." (PMID 38826147, 2024). "Another report suggested that treated with CQ or specific small interfering RNA (siRNA) targeting Atg5 or Beclin 1 could promote quercetin-induced cell apoptosis against gastric cancer." (PMID 36611961, 2022). "miR‐30e also interacts with other lncRNAs to negatively regulate cancer progression such as oncogenic lncRNA DLEU2 that promoted esophageal cancer through the miR‐30e/E2F7 axis and MALAT1 which acted as a molecular sponge of miR‐30e to regulate ATG5 expression and autophagy in gastric cancer." (PMID 35612714, 2022). "Furthermore, the binding of MALAT1 on miR-30 up-regulates the ATG5 expression, inducing autophagy mechanisms and creating gastric cancer cells resistant to DDP." (PMID 34947835, 2021). "Therefore, autophagy regulation mediated by the miR-30e-ATG5 axis is crucial for the anticancer function of DIM in gastric cancer cells." (PMID 31126043, 2019). "In our study, to test whether DIRAS3-induced gastric cancer cell migration depends upon autophagy, we chose to establish a stable knockdown of ATG5 in BGC-823 gastric cancer cells." (PMID 30043279, 2018). "Furthermore, to test whether DIRAS3-induced gastric cancer cell migration depends upon autophagy, we successfully knocked down autophagy-initiating factor ATG5 together with DIRAS3 overexpression in BGC-823 cells." (PMID 30043279, 2018). "It has been reported that ATG2B, ATG5, ATG9B, ATG12, and ATG16L1 are closely related to gastric cancer (GC)." (PMID 37629426, 2023). "NORAD then sponges miR-433-3p to increase the expression of autophagy-related genes ATG5 and ATG12, which helps in alleviating DNA damage and oxidative stress and eventually confers oxaliplatin resistance in gastric cancer (GC) cells." (PMID 35625948, 2022). "Simultaneously, PB2 triggered autophagy in gastric cancer cells, with enhanced LC3 staining and increased expression of Beclin1 and Atg5, while the inhibition of autophagy by 3-MA reversed the PB2-induced suppression on cell viability." (PMID 33627124, 2021). "LncRNA MALAT1 regulated miR-30e/ATG5 expression to modulate autophagy and apoptosis of SGC7901 gastric cancer cells and conferred resistance to cisplatin." (PMID 33482814, 2021). "Baseline tissue mRNA expression of MIF, Atg5, LC3A and LC3B was measured by real-time PCR in 453 patients (control 165, gastric dysplasia 82, and gastric cancer 206)." (PMID 30742638, 2019). "Immunohistochemistry analysis has identified an elevated staining intensity for autophagy related proteins such as Beclin1, Atg5, Atg8/ MAP1LC3B, and SQSTM1/p62 in gastric cancer tissue." (PMID 28109268, 2017). "The frameshift mutations with mononucleotide repeats have been found in ATG2B, ATG5, ATG9B and ATG12 genes in gastric cancer and colorectal cancer, which may be involved in cancer development by deregulating the autophagy process." (PMID 31969156, 2020).
gastric cancer (continued). "Furthermore, under propofol and cisplatin treatment, the inhibitory effect on tumour growth of gastric cancer xenograft was strengthened by downregulation of MALAT1 and ATG5 expression, which might be partly achieved via inhibition of autophagy." (PMID 32596964, 2020). "In gastric cancer (GC), the ARlncRNA MALAT1 intensifies cisplatin resistance through the stimulation of autophagy, by down-regulating miR-30b and concomitantly up-regulating ATG5." (PMID 37588204, 2024). "Autophagy markers such as LC3B and Atg5, and KLK6 which is gastric cancer biomarker, but not beclin-1, showed increased expression over 16 h after AF treatment." (PMID 27863404, 2016).